HNF1A (HNF1 homeobox A)
Diseases named in the same sentence as HNF1A in open-access papers (continued):
Sharing a sentence is not in itself a finding about the gene and the disease.
MODY (continued). "Of these cases, 80% are contributed by variants in common genes associated with maturity‐onset diabetes of the young (MODY), including glucokinase (GCK), hepatic nuclear factor (HNF)‐1A, HNF1B and HNF4A." (PMID 40966384, 2025). "Our findings align with those of a study of 224 MODY patients in Turkey, where mutations were identified in the following proportions: 65% in the GCK gene, 19% in HNF1A, 3.6% in HNF4A, 3.6% in KLF11, and 3.1% in HNF1B." (PMID 39859454, 2025). "A separate study analyzing a panel of 14 MODY-associated genes in 178 patients with a MODY phenotype from Western Siberia identified mutations in HNF4A, GCK, HNF1A, and ABCC8 genes in 38 patients." (PMID 39859454, 2025). "In HNF1A-MODY, weekly GLP-1 RA monotherapy has maintained excellent glycaemic control without hypoglycaemia, offering a clear alternative when sulfonylureas lead to weight gain or recurrent hypoglycaemic episodes." (PMID 41262822, 2025). "We therefore assessed their existing genetic evidence and performed the gene-level burden tests in a large MODY cohort, alongside two established MODY genes as positive controls (HNF1A-high penetrance, RFX6 -low penetrance)." (PMID 40779032, 2025). "This clinical response supported a presumptive diagnosis of MODY, likely the HNF1A or HNF4A subtype, although genetic confirmation is pending due to cost constraints." (PMID 40777711, 2025). "Of the 10 known MODY-associated TF genes, the three most common ones alone are estimated to account for more than two-thirds of all MODY cases: HNF1A (52%), HNF4A (10%), and HNF1B (6%)." (PMID 41356216, 2025). "Herein we describe the case of a patient affected by HNF1A-MODY treated effectively and safely with SGLT2i as an add-on therapy to sulfonylurea." (PMID 39903441, 2025). "This has changed the focus from only testing the most common MODY subtypes (HNF1A, HNF4A, and GCK) to testing for all subtypes." (PMID 40819284, 2025). "In contrast, genetic testing of 272 German and Austrian children with suspected MODY revealed GCK mutations in 62% of cases, HNF1A mutations in 31%, and HNF4A mutations in 4%." (PMID 41153735, 2025). "Nearly 90% of MODY cases are caused by variants in glucokinase (GCK, MODY2), hepatocyte nuclear factor 1-alpha (HNF1A, MODY3), or hepatocyte nuclear factor 4-alpha (HNF4A, MODY1), although the distribution of subtypes varies across populations." (PMID 41153735, 2025). "Targeted gene panel sequencing for 16 genes, including major forms of MODY (HNF1A-, HNF4A-, GCK- and HNF1B-MODY), was performed." (PMID 39717432, 2025). "The identification of pathogenic variants in genes such as GCK, HNF1A, and ABCC8 highlights their significance in MODY’s molecular etiology within the Russian population." (PMID 39859454, 2025). "In Europe, the United States, and many other countries, GCK-MODY and HNF1A-MODY are the two most common subtypes, together accounting for approximately 60%–90% of all MODY cases." (PMID 41367630, 2025). "Two key studies from that country have significantly advanced the understanding of MODY genetics by identifying mutations primarily in GCK, HNF1A, and HNF1B genes." (PMID 41020216, 2025). "The absence of ketosis and autoantibodies, low but preserved C-peptide levels, and robust response to sulfonylurea therapy are classic features of HNF1A-related MODY." (PMID 40777711, 2025). "So far, two other cases of SGLT2i use in patients with HNF1A-MODY have been described in the literature." (PMID 39903441, 2025). "A comprehensive analysis of MODY in sub-Saharan Africa revealed significant heterogeneity in MODY-related gene variants, with novel mutations identified in GCK, HNF1A, and ABCC8 genes." (PMID 39859454, 2025). "Typically, only one gene is thought to be causative of MODY, and a few cases of MODY have been reported to be associated with the coinheritance of GCK and HNF1A variants." (PMID 39089324, 2024).
MODY (continued). "The accumulation of data on genetically confirmed MODY associated with the coinheritance of GCK and HNF1A variants will be useful for understanding genotype–phenotype correlations." (PMID 39089324, 2024). "We explored the coinheritance of MODY with GCK and HNF1A variants in this and past cases and found that careful clinical follow-up is required to firmly establish phenotypic features." (PMID 39089324, 2024). "Among Japanese patients with MODY, mutations in GCK, HNF1A, HNF4A, and HNF1B genes were detected in 39.2%, of which the proportion of GCK gene mutations was 21.6%." (PMID 39902162, 2024). "In contrast, microvascular complications are common in HNF1A‐MODY, and current guidelines recommend sulphonylureas as first‐line treatment." (PMID 39511990, 2024). "HNF1A-MODY (also known as MODY3) is the most common MODY type worldwide with a reported prevalence among all MODY types between 15% and 52%." (PMID 39408828, 2024). "Few cases of MODY have previously been reported as being associated with the coinheritance of GCK and HNF1A variants." (PMID 39089324, 2024). "Careful clinical follow-up is required to firmly establish phenotypic features in the coinheritance of MODY with GCK and HNF1A variants." (PMID 39089324, 2024). "Our observation points to the notion that careful clinical follow-up is required to firmly establish phenotypic features in the coinheritance of MODY with GCK and HNF1A variants." (PMID 39089324, 2024). "The most prevalent forms of MODY in individuals with mutations in the HNF4A and HNF1A genes are specified by specific beta-cell dysfunction." (PMID 39902162, 2024). "Pathogenic variants in the glucokinase gene (GCK‐MODY), in hepatocyte nuclear factor 1‐alpha (HNF1A‐MODY), and HNF4A are the most common causes, accounting for >90% of all MODY types in the UK, Europe, and the United States." (PMID 39511990, 2024). "A comparison of clinical features previously reported patient and currently reported by one of the coinheritance of MODY with GCK and HNF1A variants is tabulated." (PMID 39089324, 2024). "The majority of MODY cases result from mutations in the GCK genes encoding glucokinase (GCK MODY) and the hepatocyte nuclear factor genes HNF1A and HNF4A." (PMID 39420387, 2024). "Data on the clinical follow-up of individuals with the coinheritance of GCK and HNF1A in MODY are scarce." (PMID 39089324, 2024). "Clinically, patients with HNF1A-MODY frequently present with gradually progressive hyperglycemia but usually without DKA, on one hand, or obesity and signs of insulin resistance on the other." (PMID 39408828, 2024). "At least 14 different forms of MODY are known to date, of which HNF1A MODY is the most common (30%-65%) subtype." (PMID 39420905, 2024). "Glucosuria, which is more frequent in HNF1A-MODY patients, is a biochemical feature also reported in R85W carriers." (PMID 38433330, 2024). "Despite substantial population-based differences, GCK-MODY and HNF1A-MODY are the most prevalent, accounting for 90% of all MODY cases." (PMID 38980630, 2024). "Treatment with glimepiride or liraglutide in HNF1A-MODY patients can achieve equivalent FPG and postprandial glucose excursions, and liraglutide has a lower risk of mild hypoglycemia." (PMID 37711893, 2023). "GCK‐MODY is already known to cause mild hyperglycemia, and our study results also showed that there were lower HbA1c and lower FPG of GCK‐MODY compared to HNF1A‐MODY in both subgroups." (PMID 37226652, 2023). "The present study included individuals with subtypes of MODY in addition to HNF1A and GCK, which are the most prevalent." (PMID 36747290, 2023). "The most common subtypes are MODY caused by glucokinase gene mutations (GCK) and MODY caused by Nuclear transcription Factor-1 Alpha (HNF1A) gene mutations." (PMID 37511676, 2023). "In that study, cut-off points for the probability of MODY > 75% and > 62% were found for patients with HNF1A-MODY and GCK-MODY, respectively." (PMID 36747290, 2023).
MODY (continued). "Our study showed that probands with GCK‐MODY were about 0.65 years younger than those with HNF1A‐MODY at diagnosis." (PMID 37226652, 2023). "Other common pathogenic variants for MODY were identified in the genes GCK and HNF1A, variants of which were identified in three different patients each." (PMID 37327085, 2023). "In HNF1A-MODY patients, low-dose gliclazide, a sulphonylurea, was found to improve hyperglucagonemia after a glucose challenge." (PMID 37159865, 2023). "Mutations in fourteen different genes have been so far reported to cause several MODY subtypes (OMIM # 606391), the most common of which are due to mutations in GCK, HNF1A, HNF4A and HNF1B." (PMID 35052457, 2022). "Understanding the role of the HNF1A gene and the pathophysiology of HNF1A-MODY has been difficult because of the limited access to islets of affected individuals." (PMID 35918471, 2022). "LOF mutations in HNF1A, HNF1B and HNF4A, all leading to defective insulin secretion and reduced β-cells mass, cause some forms of MODY possibly associated with kidney and/or liver abnormalities." (PMID 35052457, 2022). "The best‐known examples of precision medicine in MODY are seen in patients with HNF1A, HNF4A and GCK MODY." (PMID 35445424, 2022). "Some variants with substantial expression effects are associated with MODY, such as promoter mutations in GCK, HNF1A or HNF4A or neonatal diabetes with SNPs in the CC element of the INS promoter." (PMID 35008927, 2022). "Our study is the first GWAS of genetic determinants of age of disease onset in HNF1A-MODY patients in a large patient group." (PMID 36104811, 2022). "HNF1A-MODY manifests, usually, in the first 2–3 decades of life with mild symptoms (polyuria, polydipsia) or as asymptomatic postprandial hyperglycemia, without ketosis or ketoacidosis." (PMID 35052457, 2022). "While sulfonylureas can be used to treat patients with HNF1A-MODY effectively, insulin dependence is common after years of treatment." (PMID 35918471, 2022). "Approximately 70% of the MODY clinical cases in all the studied populations are caused by pathogenic variants in the genes GCK and HNF1A, MODY2 and MODY3, respectively." (PMID 36361703, 2022). "Within this subgroup, ten individuals (26%) tested positive for MODY (HNF1A: 7 patients, GCK: 3 patients)." (PMID 35822264, 2022). "The authors explained that HNF1A is a transcription factor for the inflammatory marker C-reactive protein (CRP) and a master regulator of fucosylation; with variations in HNF1A triggering MODY." (PMID 35768493, 2022). "Heterozygous mutations in HNF1A are known to originate from MODY3, the most common form of MODY, characterized by a failure in glycaemic control with progressive impaired β-cell function." (PMID 36361703, 2022). "Mutations in HNF1A and HNF4A are the most frequently identified aetiologies of MODY, and combined, account for 62% of MODY cases, typically characterized by dysfunctional pancreatic β cells with accompanying liver and/or kidneys defects." (PMID 36361703, 2022). "The most commonly found cases arise from mutations in GCK, HNF4A, HNF1A and HNF1B, accounting for up to 80% of all diagnosed MODY." (PMID 35008927, 2022). "The reduced penetrance of HNF1A/HNF4A-MODY in clinically unselected cohorts was largely consistent with the setting in which they were identified." (PMID 36257325, 2022). "The HNF1a variant that causes MODY3 is the most commonly reported MODY, comprising 30% to 65% of all MODY cases." (PMID 36361808, 2022). "One limitation of current MPC is that it is only validated for the three most common subtypes of MODY (HNF4A, GCK and HNF1A) when there are at least 1 genes known to cause autosomal‐dominant monogenic diabetes." (PMID 35822264, 2022). "Our study found that patients with GCK-MODY had similar hsCRP values to those in the HNF1A-MODY group, which evidenced that the inflammatory response was also suppressed." (PMID 36387841, 2022).
MODY (continued). "Common causes of MODY are genetic defects of GCK (Glucokinase), HNF1A (hepatocyte nuclear factor 1-alpha) and HNF4A (hepatocyte nuclear factor 4-alpha), which are involved in glucose sensing and glycemic regulation." (PMID 34944640, 2021). "More than 75% of MODY cases are the outcome of mutations in four genes [Hepatocyte Nuclear Factor (HNF) 4 Alpha (HNF4A), HNF1A, HNF 1 Beta (HNF1B), and glucokinase (GCK)] but their frequency varies among tested populations." (PMID 34393998, 2021). "Previous studies that have determined the levels of N-glycan fucosylation in blood plasma using liquid chromatography (LC) methods showed the excellent performance of the glycan biomarker in differentiating HNF1A-MODY patients in large patient cohorts." (PMID 33765222, 2021). "Recently, the first MODY cases were reported in patients from Africa, where the predominant subtype was HNF1A-MODY representing 5.9% of the study population." (PMID 34299172, 2021). "HNF1A-MODY is the most common form of autosomal dominant monogenic diabetes in adults, accounting for around 50 % of all MODY cases in the UK." (PMID 33765222, 2021). "Most cases of MODY are due to mutations in GCK, HNF1a, HNF4a and HNF1b, previously known as MODY2, MODY3, MODY1, and MODY5, respectively." (PMID 33259036, 2021). "A genetic screening study among the Chinese population included 74 clinically highly suspected MODY patients from 59 unrelated families with a detection rate in HNF1A and HNF4A of 13.6% and 1.7%, respectively." (PMID 34421822, 2021). "Even though the high prevalence of vascular complications in HNF1A-MODY patients was shown in many studies, there are limited data on the underlying mechanisms for such an increased risk for vascular complications." (PMID 34299172, 2021). "Our result is roughly similar to the prevalence of GCK-MODY and HNF1A-MODY described in other populations in Europe." (PMID 34440499, 2021). "Seven out of 31 index patients (22.6%) were confirmed as MODY with variants in genes encoding GCK, HNF1A, HNF1B, HNF4A, and PDX1." (PMID 34373539, 2021). "Among these genes, heterozygous mutations in HNF1A, HNF4A, and GCK have been identified as the root cause of more than 90% of MODY cases." (PMID 34421822, 2021). "Pathogenic mutations in GCK, HNF1A, HNF1B, HNF4A, and PDX1 confirmed MODY in 7 families, giving an overall positivity rate of 22.6% in this cohort." (PMID 34373539, 2021). "The United Kingdom40 has a MODY diagnosis rate of 27% with GCK/HNF1A ratio of 0.61, which closely resembles our data (positive detection rate of 21.8% and GCK/HNF1A ratio of 0.5)." (PMID 34373539, 2021). "The most common subtypes of MODY are associated with mutations in the genes GCK, HNF1A, HNF4A, and HNF1B; among them, up to 70% of cases are caused by mutations in GCK and HNF1A." (PMID 33477506, 2021). "Mutations in glucokinase (GCK), hepatocyte nuclear factor-1 homeobox A (HNF1A), and hepatocyte nuclear factor-4 homeobox A (HNF4A) are the most common causes of MODY." (PMID 32528556, 2020). "In this study, a cutoff for MODY probability of > 75% and >62%, based on MPC, was found in all patients with HNF1A and GCK mutations, respectively." (PMID 31576961, 2020). "The HNF1A gene is located on 12q24.31 and encodes hepatocyte nuclear factor 1-alpha (HNF-1α), which is associated with maturity-onset diabetes of the young (MODY)." (PMID 33004870, 2020). "A study demonstrated that 80% of patients with HNF1A-MODY treated with sulfonylurea therapy remained insulin independent at 84 months of follow-up." (PMID 32528556, 2020). "HNF1A was the only MODY gene sequenced in this individual as genetic testing was performed before the advent of the targeted MODY gene exome sequencing panel which is the current diagnostic procedure." (PMID 32910913, 2020). "Almost 30% of patients with HNF1A-MODY are overweight or obese, making differential diagnosis between HNF1A and familial young onset type 2 diabetes even more challenging." (PMID 32528556, 2020).
MODY (continued). "Even a slight increase in the median fluorescence intensity (MFI) in one of the HNF1A-MODY patients in comparison to control 2 was found." (PMID 31739614, 2019). "After genetic analysis, diabetics (n = 46) with HNF1A, HNF1B, HNF4A, GCK gene mutations (diagnosed as MODY) and diabetics (n = 30) with HNF1B, HNF4A, GCK gene SNPs were excluded." (PMID 31109344, 2019). "In 216 (87%) patients, a diagnosis related to one of the three genes commonly associated with MODY (GCK, HNF1A, and HNF4A) was made, GCK accounting for 44% of all cases." (PMID 31291970, 2019). "At this stage, there are no studies showing any connection between soluble VE-cadherin and microvascular complications in HNF1A-MODY patients." (PMID 31739614, 2019). "As HNF1A-MODY patients were shown to exhibit diabetic microvascular complications, their iPSCs can be used to derive endothelial cells (ECs) and investigate possible mechanisms contributing to the complications." (PMID 31739614, 2019). "The most common MODY types are HNF1A MODY and GCK MODY, with prevalence estimates varying widely between reports, primarily due to referral patterns in different countries and due to recruitment strategies." (PMID 30778899, 2019). "In this study, we found that higher HbA1c levels and BMI at genetic diagnosis were associated with reduced success on sulfonylurea treatment in participants with HNF1A/HNF4A-MODY." (PMID 30229274, 2018). "Diagnosis of MODY is mainly relying on the sequential screening of the three marker genes like hepatocyte nuclear factor 1 alpha (HNF1α), hepatocyte nuclear factor 4 alpha (HNF4α), and glucokinase (GCK)." (PMID 29867778, 2018). "Individuals with HNF1A- or HNF4A-MODY are optimally treated with low-dose sulfonylureas because of an increased pancreatic insulin secretory response to sulfonylureas and increased insulin sensitivity to the insulin secreted." (PMID 30229274, 2018). "Currently, the vast majority of HNF1A-MODY cases in Croatia remain unidentified, therefore the affected individuals are not receiving optimal management." (PMID 29666556, 2018). "In conclusion, our study reports that HNF1A and ABCC8 are among the most frequently mutated MODY genes in south India." (PMID 29439679, 2018). "One of the most frequent forms of MODY is associated with variants in the HNF1A (hepatocyte nuclear factor 1-alpha) gene on chromosome 12, also known as HNF1A-MODY." (PMID 29666556, 2018). "Although more than 10 different genes have been associated with MODY, mutations in the GCK and HNF1A genes are the most frequent causes of MODY in all populations studied, including the Spanish population." (PMID 28052112, 2017). "The standard approach for diagnosis of MODY includes sequential screening of the first three common MODY genes which include hepatocyte nuclear factor 1alpha (HNF1A), hepatocyte nuclear factor 4 alpha (HNF4A) and Glucokinase (GCK)." (PMID 28095440, 2017). "Compared to GCK, HNF1A, HNF4A, and HNF1B, protein truncating mutations in the other MODY genes are less frequent causes of MODY." (PMID 29207974, 2017). "There are two main treatment options for HNF1A MODY in pregnancy: stop sulfonylureas pre‐pregnancy and transfer to insulin or treat with glibenclamide pre‐/early pregnancy and transfer to insulin in the second trimester." (PMID 28556992, 2017). "As the nature of the beta-cell defect in HNF1A-MODY is progressive, this treatment frequently requires further intensification with additional hypoglycemic agents." (PMID 28593615, 2017). "Mutations in the GCK, HNF1A, HNF4A, and HNF1B genes are the most common causes of MODY in the UK, and they represent different clinical characteristics respectively." (PMID 28105082, 2017). "As a result, patients with HNF1A-MODY require pharmacotherapy and often develop chronic complications." (PMID 28593615, 2017).